RNU6-1056P (RNA, U6 small nuclear 1056, pseudogene)
Gene: Small nuclear RNA gene on chromosome X (48,724,455 to 48,724,561, reverse strand). Ensembl gene ENSG00000206723.
Homologues: Orthologues: chimpanzee U6 (99% identical), macaque U6 (95% identical), rat U6 (86% identical), pig U6 (78% identical), dog U6 (77% identical), guinea pig U6 (71% identical). Paralogues in human: RNU6-1124P (89% identical), RNU6-19P (88% identical), RNU6-338P (88% identical), RNU6-43P (88% identical), RNU6-1060P (87% identical), RNU6-12P (87% identical), RNU6-13P (87% identical), RNU6-140P (87% identical), RNU6-24P (87% identical), RNU6-25P (87% identical), RNU6-29P (87% identical), RNU6-32P (87% identical), and 1285 more.